IDH1 (isocitrate dehydrogenase (NADP(+)) 1)
Diseases named in the same sentence as IDH1 in open-access papers (continued):
Sharing a sentence is not in itself a finding about the gene and the disease.
breast carcinoma (40 papers, 2011 to 2026). "This includes 2 patients with MSI-high tumors with the indication for checkpoint immunotherapy, 2 patients with ERBB2 amplification in the context of possible breast carcinoma, as well as 1 patient with IDH1 mutation." (PMID 36933203, 2023). "Low expression of IDH1 has been associated with poor prognosis in breast cancer, whilst high expression of IDH1 associated with better survival indicating that IDH1 acts as a tumour suppressor in breast cancer." (PMID 33367952, 2021). "Whilst hBCATc expression was found to be associated with HER2 subtype, expression of hBCATm and IDH1 metabolic proteins was found to be significantly increased in luminal A tumours compared with other breast cancer subtypes." (PMID 33367952, 2021). "An analysis of TCGA database revealed that low IDH1 mRNA expression levels were significantly associated with poor overall survival in patients with breast cancer (CHR, 1.80; 95% CI% 1.10-2.94; p = 0.02)." (PMID 29661250, 2018). "We first reported that the loss of IDH1 expression resulted from the aberrant overexpression of miR-32-5p and miR-92b-3p in breast cancer." (PMID 29661250, 2018). "However, the only case of IDH1 mutation was found to be reported in ER + breast cancer indicating IDH1 mutations to be a rare event in breast cancer." (PMID 33367952, 2021). "On the other hand, the low frequency of IDH1/2 mutations has been reported in breast cancer." (PMID 29661250, 2018). "Furthermore, low IDH1 expression was significantly associated with the poor prognosis in breast cancer." (PMID 29661250, 2018). "Therefore, we examined the presence of R132H mutant IDH1 in breast cancer tissues using the IHC approach, and this mutation was absent in breast cancer tissue from the 309 women (data not shown)." (PMID 29661250, 2018). "Expression of hBCATm and IDH1 correlated with luminal A breast cancer and smaller breast tumours, indicating better prognosis." (PMID 33367952, 2021). "The expression of hBCATm and IDH1 was positive in 88.3% and 90.8% of primary breast cancer cases, respectively." (PMID 33367952, 2021). "The next pathway, ESR1, which was mutated in breast cancer, received microenvironment factor S100A4 to regulate TF ETS1 and SMAD3 through signaling transduction proteins ZNF516, PIK3R1, IDH1, and AKT1." (PMID 33802957, 2021). "For example, earlier studies identified 42 tumors harboring IDH1 mutations by screening 15,531 prostate cancers (0.3%) or 43 tumors exhibiting CD117 overexpression in a cohort of 1654 breast carcinomas (2.6%)." (PMID 32144630, 2020). "In the present study, we demonstrated that IDH1 depletion in breast cancer cells led to an increase in the HIF1α protein level to promote cell migration and invasion." (PMID 29661250, 2018). "Our present study revealed that IDH1 knockdown significantly increased the migration and invasion ability of breast cancer cells by triggering their EMT." (PMID 29661250, 2018). "Together, these results indicated that the protein expression levels of IDH1 were gradually decreased during breast cancer progression." (PMID 29661250, 2018). "In summary, we observed that miR-32-5p and miR-92b-3p overexpression resulted in tumor-suppressive IDH1 silencing in breast cancer tissues compared with that in adjacent normal tissues." (PMID 29661250, 2018). "By analyzing TCGA database, we observed the same result that IDH1 expression levels were significantly lower in breast cancer compared to adjacent normal tissues (p = 0.00003)." (PMID 29661250, 2018). "Low IDH1 expression levels, particularly in combination with snail expression, served as a potential prognosis biomarker for breast cancer." (PMID 29661250, 2018).
breast carcinoma (continued). "We further assessed the mRNA expression levels of IDH1 using a real-time PCR approach, which revealed that IDH1 expression levels and transcript levels were significantly lower in breast cancer tissues than in adjacent normal tissues (p = 0.0042)." (PMID 29661250, 2018). "Herein, we reported a novel finding that the expression levels of miR-92b-3p significantly increased and promoted breast cancer invasion by silencing the expression of IDH1." (PMID 29661250, 2018). "Our data revealed that IDH1 expression levels were closely associated with early pathology and pN stages, suggesting that IDH1 contributes to the growth and migration/invasion of breast cancer cells." (PMID 29661250, 2018). "The biological functions of IDH1 were examined in breast cancer cells with IDH1 knockdown, including proliferation, migration and invasion." (PMID 29661250, 2018). "We further examined the expression levels of IDH1 in eight breast cancer cell lines, including cells with low invasive ability (MCF7, T47D, SK-BR3, MDA-MB-468, and MDA-MB-453) and cells with high invasion ability (BT549, Hs578T, and MDA-MB-231)." (PMID 29661250, 2018). "Collectively, these results demonstrated that IDH1 plays a tumor-suppressing role in the progression of breast cancer." (PMID 29661250, 2018). "We next combined the expression levels of IDH1 and snail to assess the correlation with breast cancer survival." (PMID 29661250, 2018). "Because the expression levels of IDH1 were lower in breast cancer, those miRNA candidates with elevated expression in breast cancer would have the potential to regulate IDH1." (PMID 29661250, 2018). "Our results indicated that IDH1 expression levels were significantly lower in breast cancer tissues than in adjacent normal tissues and that IDH1 played a crucial role in modulating breast cancer metastasis." (PMID 29661250, 2018). "In summary, the aberrant overexpression of oncogenic miR-32-5p and miR-92b-3p resulted in the reduction of IDH1 by directly binding at the 3′-UTR of IDH1 to promote invasion in breast cancer cells." (PMID 29661250, 2018). "The results revealed that IDH1 expression levels were significantly lower in breast cancer tissues than in adjacent normal tissues (p = 0.004)." (PMID 29661250, 2018). "The present findings revealed that the mRNA and protein expression levels of IDH1 were both significantly lower in breast cancer tissues than in adjacent normal tissues." (PMID 29661250, 2018). "Low IDH1 expression levels can promote the migration and invasion abilities of breast cancer cells by activating snail expression." (PMID 29661250, 2018). "In this study, we first reported that the IDH1 is downregulated in breast cancer and depletion of IDH1 in breast cancer cells results in accelerating breast cancer migration and invasion activities by activating snail expression." (PMID 29661250, 2018). "For the first time a synergistic mechanistic expression of IDH1 and hBCATm in luminal A breast cancer has been described, which may be mediated by upregulation of the ER-activated SREBP1 transcription factor." (PMID 33367952, 2021). "There is little evidence of IDH1 mutations in breast cancer, with only one reported case discussed in the literature." (PMID 33367952, 2021). "A patient with hormone-receptor (HR+) breast carcinoma exhibited mutant IDH1 R132L within the tumor tissue and cells in lymph nodes, which corresponded to an elevated 2HG concentration in urine (22 ng/mL vs. 1.7 ng/mL in healthy controls) and serum (1979 ng/mL vs. 105 ng/mL in healthy controls)." (PMID 31847543, 2020). "Focusing on breast cancer, c-Myc-retransformed breast cancer tissues contained substantial levels of 2HG (0.5–20 nmol/mg), despite the absence of IDH1/2 mutations." (PMID 31847543, 2020). "Furthermore, the ectopic expression of miR-32-5p and miR-92b-3p suppressed the mRNA and protein expression of IDH1 in breast cancer cells." (PMID 29661250, 2018).
breast carcinoma (continued). "Clinically, the IDH1–snail axis dysfunction might be a favorable independent marker for predicting breast cancer survival." (PMID 29661250, 2018). "Based on the previous evidence, we examined whether IDH1 knockdown could potentially accelerate the invasion ability of breast cancer cells through MAPK–HIF-1a/NFkB signaling." (PMID 29661250, 2018). "A low expression level of IDH1 in breast cancer significantly correlated with advanced stage (p = 0.012), lymph node metastasis (p = 0.018), and poor disease-specific survival (DSS) (adjusted hazard ratio (AHR), 1.57, 95% confidence interval (CI), 1.08–2.30; p = 0.02)." (PMID 29661250, 2018). "In this study, we provided a novel insight to clarify the role of IDH1 expression in breast cancer." (PMID 29661250, 2018). "Together, our data revealed that aberrantly low expression levels of IDH1, rather than IDH1 mutation, had crucial effects on the prognosis of breast cancer." (PMID 29661250, 2018). "Furthermore, the siRNA knockdown of IDH1 can promote the invasion ability of breast cancer cells, suggesting that IDH1 acts as a tumor suppressor in breast cancer progression." (PMID 29661250, 2018). "Furthermore, depletion of IDH1 in breast cancer cells results in accelerating breast cancer migration and invasion activities by activating snail expression." (PMID 29661250, 2018). "We investigated whether IDH1 protein dysfunction contributes to the clinicopathological features of breast cancer." (PMID 29661250, 2018). "Up-regulation of IDH1 has been correlated with the metastasis of human breast cancer." (PMID 22363243, 2011). "Consequently, previous observations became explainable, such as when c-Myc-retransformed breast cancer tissues were found to contain substantial levels of 2HG (1–20 nmol/mg, i.e., up to ∼20 mM) in the absence of IDH1/2 mutations." (PMID 31847543, 2020). "Multivariate logistic analysis and plotting of survival curves showed that low IDH1 expression levels were significantly associated with poor DSS (adjusted HR (AHR), 1.57; 95% CI, 1.08–2.30; p = 0.02) but not DFS (AHR, 1.40; 95% CI, 0.93–2.10; p = 0.106) in patients with breast cancer." (PMID 29661250, 2018). "IDH1 was indeed more highly expressed in DCIS than in IDC in our study and has also previously been shown to decrease with the progression of breast cancer." (PMID 40119362, 2025). "First, we examined the expression levels of IDH1 and IDH2 in breast cancer tissues and adjacent normal tissues from 10 patients using western blotting." (PMID 29661250, 2018). "QPCR analysis performed at two different time points, 48h and 72h, indicated an up-regulation of Slc1a5, GOT1 and IDH1 at 72h in FSK treated samples, hence confirming also in human breast cancer cells a role of PKA activation in glutamine metabolism." (PMID 26978032, 2016). "A deregulation of the isocitrate dehydrogenase enzyme isoforms 1 (IDH1) and 2 (IDH2) in the epithelial component of breast cancer tumors could be related to these findings." (PMID 36831625, 2023). "Univariate logistic analysis revealed that low IDH1 expression levels resulted in poor DSS (crude hazard ratio (CHR), 1.64; 95% confidence interval (CI), 1.14–2.38; p = 0.008) and DFS (CHR, 1.58; 95% CI 1.07–2.34; p = 0.023) in patients with breast cancer." (PMID 29661250, 2018). "In contrast to MDA-MB-231 cells, the proliferation of MCF7 was promoted after IDH1 knockdown, which suggested that the role of IDH1 in MCF7 cell proliferation might be slightly different in breast cancer cells with different subtypes." (PMID 29661250, 2018).
breast carcinoma (continued). "Our data suggested G6PD, IDH1 and IDH2 may carry out a novel mechanism with adriamycin resistance in breast cancer." (PMID 25818003, 2015). "IDH1 protein content is not deferentially expressed between breast cancer cells compared to IDH2." (PMID 39195531, 2024). "In gliomas, hBCATm has been identified as a negative prognostic marker in IDH1-WT gliomas, supporting the hypothesis for hBCATm to contribute to tumour progression in the absence of IDH mutation, which is a rare event in breast cancer." (PMID 33367952, 2021). "Notably, the IDH1–snail axis supported our finding in breast cancer on the negative correlation between IDH1 and snail expression in clinical samples." (PMID 29661250, 2018). "Indeed, sterol response element-binding protein 1 (SREBP1) has been demonstrated to regulate hBCATm, in pancreatic ductal adenocarcinoma and IDH1, but not IDH2 expression, in breast cancer." (PMID 33367952, 2021). "However, even wild-type IDH1 and IDH2, notably under shifts toward reductive carboxylation glutaminolysis or changes in other enzymes, lead to “intermediate” 0.01–0.1 mM 2HG levels, for example, in breast carcinoma compared with 10−8M in noncancer cells." (PMID 31847543, 2020).
oligoastrocytoma (32 papers, 2012 to 2025). A WHO grade II tumor composed of a conspicuous mixture of two distinct neoplastic cell types morphologically resembling the tumor cells in oligodendroglioma and diffuse astrocytoma. "In this study, the detection of the majority of IDH1/2 mutations in oligoastrocytoma tumors supports this conjecture." (PMID 33552543, 2020). "The presence of the TERT promoter and IDH1/2 mutational status may be particularly useful to refine the classification of “mixed” oligoastrocytomas." (PMID 24722048, 2014). "Patient stratification for the histological type revealed that EMP3 promoter hypermethylation was significantly associated with IDH1/IDH2 mutations in astrocytic tumors (P = 0.0088), GBMs included (P = 0.0012), in oligodendroglial tumors (P = 0.0006), and in oligoastrocytomas (P = 0.0095)." (PMID 24083241, 2013).
astrocytic tumor (30 papers, 2012 to 2025). A glial tumor of the brain or spinal cord showing astrocytic differentiation. "Patients with IDH1-R132H positive or ATRX loss astrocytic tumors had a longer progressive- free survival (p<0.0001, p=0.0044, respectively)." (PMID 27713914, 2016). "In contrast to astrocytic tumors, ODs have a better prognosis associated with LOH1p/19q and IDH1 mutation." (PMID 26468983, 2015). "Notwithstanding, our findings underline the fact that in high-grade astrocytic tumors H3K9 is trimethylated by an as yet undefined IDH1 mutant independent mechanism deregulating the complex dynamic balance between methyltransferases and demethylases." (PMID 25602259, 2015). "Low ATRX expression closely overlapped with mutations in IDH1/2 (P<0.0001) in astrocytic tumors across WHO grades II–IV." (PMID 24810474, 2014). "This is the critical reason why we defined astrocytic tumors using IDH1/2 mutational status plus ATRX or Ki67 expression, a common proliferation marker in clinical practice." (PMID 24810474, 2014). "Of note, when present IDH1- mutations always affected both, the oligodendroglial and the astrocytic tumor component of the microdissected tumors." (PMID 22844452, 2012). "For astrocytic tumors, the incidences of IDH1/2 mutation between different sides of the brain (42.6%, 54.2% and 30.0%, respectively) were not significantly different." (PMID 22427879, 2012). "The incidence of IDH1/2 mutation in astrocytic tumors of parietal origin (0.0%) was significantly lower than that of non-parietal origin (51.0%) (P = 0.003)." (PMID 22427879, 2012). "A previous study reported IDH1 mutations could reduce the pericyte coverage of microvessels in astrocytic tumors by inhibiting the expression of angiogenesis factors." (PMID 32582544, 2020). "Therefore, the only verified prognostic markers for astrocytic tumors remain the IDH1/2 mutation, 1p/19q translocation, and the presence of an MGMT mutation." (PMID 28845375, 2017). "Therefore, to further refine the molecular classification of astrocytic tumors, we incorporated the other two prognostic markers into the model, IDH1/2 mutational status and Ki-67 protein expression, which were also associated with the clinical outcome of patients with astrocytic tumors.." (PMID 24810474, 2014). "Thus, we speculated that IDH1/2 mutations accompanied by ATRX or Ki-67 may represent a distinct biological process during the development of astrocytic tumors from the original tumor cells." (PMID 24810474, 2014). "ATRX, IDH1/2, and Ki-67 collaboratively define three distinct subgroups of astrocytic tumors, offering a molecular classification that transcends the conventional WHO grading system." (PMID 40282990, 2025). "Associations between WT1 expression level and the prognostic indicators of astrocytic tumors including: age IDH1 status apoptotic (Bcl2 index) and cell proliferation (Ki67 index) markers are further studied." (PMID 32856872, 2020). "In this study, we detected ATRX, IDH1-R132H and Ki-67 by immunohistochemistry and characterized three prognostic subgroups of astrocytic tumors (referred to as A1, A2 and A3)." (PMID 27713914, 2016). "Then we evaluated the value of ATRX, IDH1- R132H and Ki-67 for predicting the progression of astrocytic tumors." (PMID 27713914, 2016).